CD38 (CD38 molecule)
Diseases named in the same sentence as CD38 in open-access papers (continued):
Sharing a sentence is not in itself a finding about the gene and the disease.
multiple myeloma (continued). "Apparently, this CD38 molecule is distinct from CD38 on other cells because a lamprey monoclonal antibody that recognizes a unique epitope of the CD38 ectoenzyme specifically reacts with plasmablasts and plasma cells in healthy individuals and in most human multiple myelomas." (PMID 31024553, 2019). "In addition, drugs with a different mechanism of action, such as the histone deacetylase inhibitor and the monoclonal antibodies (MoAb) targeting SLAMF7 or CD38, are a part of the anti-myeloma armamentarium and are very important for heavily pretreated or double refractory to a PI and IMiD patients." (PMID 31842517, 2019). "CD38 signals may operate on a myeloma background by modulating miRNAs." (PMID 31118070, 2019). "However, the pathological significance of CD38 expression in multiple myeloma cells remains unclear." (PMID 30631755, 2018). "Moreover, crosslinks formed between CD38-bound antibody on MM cells and Fcγ receptors on effector cells may play a key role in direct cytotoxicity of myeloma cells by inducing apoptosis through disruption of intracellular signaling cascades." (PMID 30544512, 2018). "Moreover, CD38 expression is a prognostic biomarker in B cell acute lymphoblastic leukemia and may play a role in multiple myeloma and acute promyelocytic leukemia." (PMID 30042766, 2018). "In fact, MM pre-clinical studies showed that checkpoint blockade efficacy could be improved if associated with treatments able to intensify the activity of myeloma-reactive T cells, such as transplantation, cellular therapies, anti-CD38 antibodies, chimeric antigen receptor (CAR) T cells, and IMiDs." (PMID 30538704, 2018). "Furthermore, various preclinical studies, case reports, and clinical trials have already demonstrated promising results of CD38 antibodies in other malignancies such NK/T cell lymphoma, T-cell acute lymphoblastic leukemia, and immunoglobulin light-chain amyloidosis." (PMID 30294326, 2018). "In patients with AL-amyloidosis, CD38-expression is neither associated with the number of affected organs, involvement of the heart as the most critical organ, nor the surrogate marker NT-proBNP (<332 vs. ≥332 ng/l) or the Mayo2004-score." (PMID 30079070, 2018). "The results from the CASTOR trial demonstrate the advantages of combination therapy with daratumumab and bortezomib, which may stem from the enhanced direct cytotoxicity noted against myeloma cells during in vitro preclinical studies when antibodies targeting CD38 were combined with PIs." (PMID 29900019, 2017). "In addition, myeloma cells generally live in closed environments located in the bone and CD38 expression by these cells may be functional to growth and escape strategies." (PMID 26393653, 2015). "Finally, the effects induced by therapeutic anti-CD38 monoclonal antibodies provide proof-of-concept that human multiple myeloma might use CD38 and its main substrate NAD+ in generating local tolerance." (PMID 26393653, 2015). "However, still elusive is the functional role exerted by CD38 in plasma cells and in myeloma." (PMID 24489445, 2013). "Thus, the combination of CD38 and CD138 is superior to CD38 alone for identifying CD45+ myeloma." (PMID 24744630, 2012). "However, it is clear that CD38+ CD45−/dim gating may fail to identify myeloma mainly or partly composed of CD45+ PCs." (PMID 23021410, 2012). "Various target antigens, including BCMA, CD19, CD38, CD44v6, CD138, GPRC5D, kappa light chain, FcRH5, CS1, integrin β7, and NKG2D, have been used to engineer CAR T cells to kill myeloma cells, with encouraging results." (PMID 40078993, 2025). "Second-line targets, such as SLAMF7, CD38, CD138, TACI, and APRIL, possess biological validity, high expression on myeloma cells, and proven therapeutic potential in preclinical and early clinical trials." (PMID 40649828, 2025). "Both subpopulations had prototypical multiple myeloma characteristics of high CD138, CD38, and clonally restricted kappa light chain expression." (PMID 39699274, 2025).
multiple myeloma (continued). "Based on our analysis, the most likely targets for clinical approval in disease groups such as lymphoma and multiple myeloma are CD20, CD22 (or in combination with CD19), CD38, BAFFR, CD7, and CD5." (PMID 40726984, 2025). "By examining the expression patterns of specific markers, such as CD138, CD38, and BCMA, immunophenotyping helps to accurately identify and differentiate myeloma cells from normal cells." (PMID 40977723, 2025). "Results of phase I clinical trials (for example, NCT03473496) have confirmed the relative safety and efficacy of CD38-specific CAR T cells in patients with relapsing and refractory multiple myeloma." (PMID 40649828, 2025). "For this purpose, we employed lymphoma and multiple myeloma cell line models expressing CD20 and/or CD38, respectively, as targets for clinically used antibodies." (PMID 40163355, 2025). "The introduction of anti-CD38 monoclonal antibodies, TCEs, and CAR-T therapy has ushered in a transformative era for elderly patients with multiple myeloma." (PMID 40805272, 2025). "Sixty percent of the patients (12 out of 20) in their study had CBLs that expressed CD34, CD38, CD184, CD31, CD50, and the same immunoglobulin light chain as the patients’ known myeloma cells." (PMID 40977723, 2025). "Dual-targeting platforms, simultaneously recognizing plasma cell antigens (e.g., CD38, BCMA) and microenvironmental markers (e.g., CXCR4 or PDGFR-β), have shown over 90% internalization in myeloma cells and enhanced stromal penetration in preclinical models." (PMID 41471085, 2025). "constructed a humanized TanCAR targeting both BCMA and CD38 (BM38 CAR) and evaluated its anti-myeloma activity both in vitro and in vivo." (PMID 40092990, 2025). "Multiple myeloma is also treated through targeting B cell Maturation Antigen (BCMA) and CD38, a transmembrane glycoprotein responsible for cell adhesion and signal transduction." (PMID 41350493, 2025). "The conclusion is that the trispecific SAR442257 operates via dual targeting of CD38 and CD28 on myeloma cells and of CD3 and CD28 on T lymphocytes, showing superior MM killing compared to bispecific antibodies." (PMID 40013150, 2025). "Together with the CD38-, SLAMF7-, and BCMA-focused platforms, talquetamab contributes to the emerging paradigm of multi-antigen, multi-platform immunotherapy in multiple myeloma, enabling more personalized and strategically layered treatment approaches." (PMID 41511330, 2025). "Bispecific antibodies developed for multiple myeloma currently target B-cell maturation antigen (BCMA), G protein–coupled receptor, class C, group 5, member D (GPRC5D), Fc receptor-like 5 (FcRL5), or CD-38." (PMID 39754658, 2025). "While both CD38 and CD138 are expressed at elevated levels on multiple myeloma, they are also found on a variety of healthy tissues." (PMID 39606234, 2024). "CD38-targeted antibodies for multiple myeloma induce apoptosis, ADCC, and phagocytosis while depleting CD38+ immune regulatory cells." (PMID 38785789, 2024). "CD38 and CD47 are expressed in many hematologic malignancies, including multiple myeloma (MM), B-cell non-Hodgkin lymphoma (NHL), B-cell acute lymphoblastic leukemia (ALL), and B-cell chronic lymphocytic leukemia (CLL)." (PMID 38983860, 2024). "Since tinostamustine upregulated CD38 and MICA/B expression in different myeloma cell lines, we wondered if this effect was translated into an improvement of daratumumab-mediated ADCC." (PMID 38731936, 2024). "The carrier was attached to the T cell targeting molecule, anti-CD3, and to different monoclonal antibodies that target a multiple myeloma antigen (BCMA, CS1, or CD38), increasing the poor half-life of conventional BiTEs." (PMID 37587290, 2024). "Notable among these are CD38, CD138, and the B-cell maturation antigen (BCMA), which have been successfully targeted by monoclonal antibodies in the treatment of multiple myeloma." (PMID 38254683, 2024).
multiple myeloma (continued). "It was found that reducing the affinity of CD38-CAR T cells by approximately 1,000-fold was most effective at lysing CD38+ multiple myeloma (MM) cells." (PMID 39538305, 2024). "This is the first study to validate the R2-ISS with novel agents, including anti-CD38 monoclonal antibodies, and to show that R2-ISS, as a prognostic scoring system, can be applied to patients with relapsed/refractory multiple myeloma." (PMID 39609425, 2024). "In the context of Multiple Myeloma, notable antigens such as CD19, CD38, CD138, BCMA (B-cell Maturation Antigen), Kappa (κ) light chain, SLAMF7, NKG2D, and GPRC5D have been identified as effective targets for CAR T-cell therapy." (PMID 38438559, 2024). "Typically, relapsed refractory multiple myeloma (RRMM) exhibits more aggressive behavior, leading to a shortened survival for patients who have become resistant to CD38 mAbs." (PMID 38421887, 2024). "In vitro studies on multiple myeloma cell lines and purified CD38 protein have shown that ISA inhibits both CD38 hydrolase and cyclase activity, while DARA only partially inhibits cyclase activity and enhances hydrolase activity." (PMID 39364393, 2024). "Belantamab mafodotin is the first‐in‐class antibody‐drug conjugates (ADC) targeting B‐cell maturation antigen (BCMA) approved for relapsed/refractory multiple myeloma (RRMM) who received at least four prior LOTs including a PI, an IMiD, and an anti‐CD38 mAb." (PMID 38895069, 2024). "Targeting CD38 with the anti-CD38 antibody daratumumab and isatuximab are FDA-approved for the treatment of patients with multiple myeloma." (PMID 38533509, 2024). "An open-label phase 1 clinical trial has been initiated to explore the therapeutic efficacy of CAR2 anti-CD38 A2 CAR T cells when used as a monotherapy for the management of relapsed and refractory multiple myeloma patients (NCT03464916)." (PMID 38006053, 2023). "Food and drug administration(FDA) has approved daratumumab and isatuximab targeting CD38 and elotuzumab targeting SLAM7 for the treatment of myeloma." (PMID 37275861, 2023). "For instance, a CD38/CD3 Bi-Ab (ISB-1342) that targets tumor cells (via CD38) and immune effector T cells (via CD3) is in phase II for relapsed/refractory multiple myeloma (R/R MM) (NCT033309111); the putative efficacy of ISB-1342 in CLL remains to be tested." (PMID 37760777, 2023). "Soon after, an anti-CD38 CAR-T cell, CarvyktiTM (ciltacabtagene autoleucel) was authorized by the FDA in r/r multiple myeloma." (PMID 36831349, 2023). "They demonstrated that the CD38 knockout NK cells exhibited a more prominent metabolic profile, which increased ADCC-mediated killing of CD38+ multiple myeloma cell lines and patient-derived samples." (PMID 36768432, 2023). "Thus, the anti-CD38 MoAb may be effective for LEN-refractory myeloma." (PMID 38004369, 2023). "Researchers have also evaluated the feasibility of CD38-CAR-T cell therapy in a variety of lymphoid neoplasms, including multiple myeloma and NKTCL." (PMID 37649020, 2023). "Dermal fibroblasts activated by contact with multiple myeloma RPMI 8226 cells induce growth arrest and alter the expression of CD38, CD45, and CD138 in myeloma cells consistent with dedifferentiation, inflammation, and progression toward dormancy." (PMID 37046676, 2023). "Notably, outcomes for patients with myeloma have been improving dramatically with the advent of novel therapies, and especially of immunomodulatory agents (IMiDs), proteasome inhibitors (PIs), anti-CD38 antibodies, and B-cell maturation antigen (BCMA)-targeted drugs." (PMID 37111346, 2023). "Despite the development of anti-myeloma therapeutics, such as proteasome inhibitors, immunomodulatory drugs, anti-CD38 monoclonal antibodies, and autologous stem cell transplantation (ASCT), multiple myeloma remains incurable." (PMID 37173885, 2023).
multiple myeloma (continued). "While the prognostic significance of the presence of CD38 on myeloblasts in acute myeloblastic leukemia (AML) in adults, and in multiple myeloma or chronic lymphocytic leukemia (CLL) is documented, the role of CD38 in BCP-ALL is unclear." (PMID 37675394, 2023). "Daratumumab is a human monoclonal antibody that targets CD38, approved by FDA and EMA for the treatment of multiple myeloma." (PMID 37332353, 2023). "As a monoclonal antibody targeting CD38, daratumumab (DARA) has dramatically improved the therapeutic outcome of patients with myeloma." (PMID 36428748, 2022). "Accordingly, a phase 1 dose escalation and expansion study with an anti-CD38 Ab, CID-103, is currently recruiting previously treated, relapsed or refractory multiple myeloma patients (ClinicalTrials.gov Identifier: NCT04758767)." (PMID 36428727, 2022). "Staining with myeloma cell markers CD138, CD38, CD56, and intracellular markers for κ and λ showed high purity of the MM cells." (PMID 35148457, 2022). "In the co-culture model of primary multiple myeloma cells and BMSC, TNT-mediated mitochondrial transfer to multiple myeloma cells is inhibited by the shRNA-mediated knockdown of CD38." (PMID 36551198, 2022). "A panel of CD38 and CD138/CD19/CD45/CD56/CD117 markers is considered the immunophenotypic diagnosis of plasma cell myeloma." (PMID 35004078, 2022). "The results show that all three CD38-specific HLE-nano-BiKEs (E1, E2, E3) as well as daratumumab effectively mediated NK-cell cytotoxicity against LP-1 myeloma cells." (PMID 35651607, 2022). "In patients with multiple myeloma, daratumumab treatment can deplete, not only the cancer, but also MDSC, Treg and regulatory B cells that express CD38." (PMID 35414042, 2022). "We then stained primary BM mononuclear cells from multiple myeloma patients to determine their expression of CD138 and CD38 markers along with mAb 14-25-9 staining." (PMID 35563109, 2022). "Our results demonstrate the efficacy of CD38-specific HLE-nano-BiKEs in vitro and ex vivo, warranting further preclinical evaluation in vivo of their therapeutic potential for the treatment of multiple myeloma." (PMID 35651607, 2022). "The CD38 antigen is also expressed by many BCP- and T-ALL cells, and both daratumumab and isatuximab, the second CD38 antibody approved for myeloma therapy, are being tested in clinical trials." (PMID 36052078, 2022). "Targeting CAMs such as CD38 and CD138/SDC1 with monoclonal antibodies have achieved promising results in multiple myeloma." (PMID 36522654, 2022). "We analyzed the morphology of the patient primary myeloma cells for expression levels of MHC I, MICA, MICB, ULBP1, ULBP2/5/6, HLA-E, CD38 (n = 12), CD112, CD155, ICAM-1 and PD-L1 (n =5) using flow cytometry." (PMID 35413499, 2022). "Today, the armamentarium of anti-CD38 antibodies includes daratumumab and recently isatuximab, both FDA approved in myeloma therapy." (PMID 35251370, 2022). "Since healthy cells also express CD38, it would be advantageous to develop CAR cells that specifically kill CD38 overexpressing myeloma cells." (PMID 36405759, 2022). "CD38-specific CAR-T cell therapy has also been shown to be effective in vitro and in vivo against hematological malignancies such as myeloma and B-cell non-Hodgkin’s lymphoma." (PMID 35906622, 2022). "Many T-ALL cells express CD38 on their surface, which can be targeted by the CD38 antibody daratumumab (DARA), approved for the treatment of multiple myeloma." (PMID 36052078, 2022). "In contrast, both CD38 antibodies efficiently recruit immune cells for ADCC and phagocytosis of myeloma cells." (PMID 35784366, 2022). "In summary, we here provide proof of principle for the efficacy of CD38-specific HLE-nano-BiKEs in vitro and ex vivo, warranting further preclinical evaluation in vivo of their therapeutic potential for the treatment of multiple myeloma." (PMID 35651607, 2022).
multiple myeloma (continued). "Several CD38-targeting antibodies, daratumumab, isatuximab, and MOR202, have been developed for the treatment of multiple myeloma." (PMID 36439479, 2022). "Tumor cells from our myeloma PDX expressed CD138 and CD38 with a mature plasma-like morphology and atypic nucleus." (PMID 35992875, 2022). "By this means, FT538 can be used in combination with the anti-CD38 antibody daratumumab, enabling ADCC of CD38-expressing myeloma cells while avoiding fratricide induced by upregulated CD38 expression in activated NK cells." (PMID 34897554, 2021). "Based on the favorable co-expression of CD38 and SLAMF7 antigen at high levels on MM, we tested hemibodies in vivo using myeloma xenografts and human peripheral blood mononuclear cells (PBMCs) in a humanized immunodeficient NOD SCID Il2rg−/− (NSG) mouse model." (PMID 33420283, 2021). "CD19, SDC1 (CD138), CD38, SLAMF7, and TNFRSF17 (BCMA) were selected for targeting multiple myeloma (MM)." (PMID 34975912, 2021). "After informed consent was obtained, we next assayed expression levels of the BCMA, CD38, and SLAMF7 antigens on 30 primary myeloma cells from clinical bone marrow samples collected at our institution." (PMID 33420283, 2021). "Myeloma cells were selected using anti-CD138 magnetic beads and more than 95% of the purified cells expressed CD138 and CD38." (PMID 34482362, 2021). "CD38 and CD319, which is identified with SLAMF-7, are expressed independently of maturation of myeloma cells." (PMID 33435539, 2021). "Here we show that hemibodies addressing CD38 and SLAMF7 recruit T cells for the exquisite elimination of dual antigen positive multiple myeloma cells while leaving single antigen positive bystanders unharmed." (PMID 33420283, 2021). "Among others, BCMA, CD19, CD38, and CD138 expressing on myeloma cells are mostly targeted by CAR-T cells." (PMID 33781320, 2021). "When using the same experimental setup with multiple myeloma cells as targets, we observed an ADCC effect with the anti-CD38 antibody daratumumab that was more similar to the degranulation effect." (PMID 34203549, 2021). "This in line with the results of our previous studies showing that human CD38-specific nanobody-based hcAbs potently induced ADCC of several human lymphoma and myeloma cell lines, including LP-1 myeloma, CA-46 and Daudi Burkitt lymphoma." (PMID 34539634, 2021). "Precisely, a hemibody pair addressing CD38 and SLAMF7 redirects T cells against dual antigen-positive myeloma cells in vitro and in vivo, while sparing single antigen-positive bystanders." (PMID 33420283, 2021). "The clinical studies have identified several numbers of target antigens expressed on abnormal plasma cells in multiple myeloma, including CD19, CD38, CD138, SLAMF7, kappa light chain, B cell maturation antigen (BCMA), and SLAMF7." (PMID 33781320, 2021). "On the other hand, we know that killing of myeloma cells with daratumumab mediated by CDC, ADCP, or ADCC is more efficient when CD38 expression is high." (PMID 32041300, 2020). "As target cells, we chose established multiple myeloma (LP-1, RPMI-8226) and Burkitt lymphoma cell lines (CA-46, Daudi) with known high cell surface levels of CD38." (PMID 32013131, 2020). "In this study, we synthesized and tested novel drug-loaded, CD38- and CD138-targeted nanoparticles for the treatment for multiple myeloma." (PMID 33138841, 2020). "The anti-CD38 monoclonal antibody (mAb), daratumumab, is currently approved by the FDA for the treatment of relapsed/refractory multiple myeloma both as monotherapy and in combination with other chemotherapeutic drugs." (PMID 33003418, 2020). "The results confirmed high cell surface levels of CD38 on both HEK cells stably transfected with CD38 and on LP-1 multiple myeloma cells endogenously expressing CD38, but only marginal levels of CD39, CD73, P2X7, or Adora2a." (PMID 33396591, 2020).